ARID1A (AT-rich interaction domain 1A)
Diseases named in the same sentence as ARID1A in open-access papers (continued):
Sharing a sentence is not in itself a finding about the gene and the disease.
lymphoma (14 papers, 2016 to 2025). A malignant (clonal) proliferation of B- lymphocytes or T- lymphocytes which involves the lymph nodes, bone marrow and/or extranodal sites. "The reduced FAS levels induced by ARID1A loss rendered lymphoma cells resistant to both soluble and T cell membrane-anchored FASLG-induced apoptosis, and significantly diminished CAR T cell killing in functional experiments." (PMID 39843653, 2025). "Overall, our experiments demonstrate that ARID1A loss leads to reduced FAS levels on lymphoma cells, making them more resistant to apoptosis induced by both soluble and membrane-bound FAS ligand, including CAR T cells." (PMID 39843653, 2025). "We also found high frequency of ARID1A mutations among bladder (8/31), ovarian (14/61), pancreatic (10/48), lymphoma (8/41), colorectal (12/67) and gastric (7/40) cancer cell lines." (PMID 36980292, 2023). "Mutations in ARID1A result in reduced chromatin accessibility, and loss of ARID1A expression has been associated with a shift towards a memory B cell-like state associated with increased risk of progression to aggressive lymphoma." (PMID 40943058, 2025). "Mutations of major interest for the GIT and lymphomas are appearing in ARID1A." (PMID 31581674, 2019). "ARID1A is recurrently mutated in several cancer types, including lymphomas." (PMID 27590521, 2016). "In summary, we have elucidated the molecular mechanism of reduced FAS expression in ARID1A mutant lymphoma cells and demonstrated that this promotes functionally and potentially clinically relevant escape from T cell mediated killing." (PMID 39843653, 2025). "In B cells, precise intervention of ARID1A is crucial for maintaining normal B cell function and preventing lymphoma development." (PMID 40342423, 2025). "Functional experiments in BCL2-translocated lymphoma cells demonstrated that ARID1A is directly involved in the regulation of FAS, and ARID1A loss leads to decreased FAS protein and gene expression." (PMID 39843653, 2025). "A similarphenotype has been reported in ARID1A-mutant lymphoma cells, suggesting further investigation will beneeded to clarify the mechanism of action of SWI/SNF-targeting therapeutics inDLBCL." (PMID 39029462, 2024). "Then, we overexpressed RUNX3 in lymphoma cells with ARID1A loss (het), which, unlike HEK 293 T cells, endogenously express ETS1." (PMID 39843653, 2025). "Noteworthy, ARID1A at 1p36.11 and ATM at 11q22.3 both map on significant narrow chromosome focal deletions in SS, a finding that further underlines the pathogenic role of these two genes in this lymphoma." (PMID 40918137, 2025). "While conjugate formation of lymphoma cells and T cells were not affected by ARID1A genotype, cells with ARID1A loss were less sensitive to T cell-mediated apoptosis, and overexpression of RUNX3 restored sensitivity towards T cell-mediated killing." (PMID 39843653, 2025). "Importantly, lymphoma cells with ARID1A loss (het and KO) exhibited significantly reduced susceptibility to CD19-CAR T cell-mediated killing, while re-expression of ARID1A in ARID1Ahet cells restored CAR T cell toxicity." (PMID 39843653, 2025). "We co-cultured luciferized lymphoma cells, with and without ARID1A loss (het and KO), with CD19-targeting CAR T cells." (PMID 39843653, 2025). "ARID1A mutations are reported in numerous cancers and lymphomas and therefore does not seem really helpful in isolation." (PMID 37081015, 2023). "Therefore, we co-cultured CFSE-labeled lymphoma cells (OCI-Ly8) with or without ARID1A loss (ARID1Ahet or ARID1AKOvs ARID1AWT clones) with VDP-labeled T cells (CD8+) from five different healthy donors." (PMID 39843653, 2025). "Lastly, while Arid1a mutations (and mutations in other cBAF subunits) are frequently associated with germinal center-derived lymphomas, Arid1a loss by itself was not sufficient to induce malignant transformation of B cells, even in mice that were aged up to 12 months (not shown)." (PMID 38313292, 2024).
lymphoma (continued). "These include AKT3, ERCC5 and maybe ARID1A as general MMR-D targets, but also POLE as lymphoma-specific neoantigen." (PMID 31581674, 2019).
clear cell renal cell carcinoma (13 papers, 2012 to 2026). "In a previous study regarding clear cell renal cell carcinoma, ARID1A was identified as a direct target gene of miR-144-3p." (PMID 35197108, 2022). "In these cancers, some established tumor suppressive genes were found to be the direct targets of miR-144, such as PTEN in nasopharyngeal carcinoma, and ARID1A in clear cell renal cell carcinoma." (PMID 32351538, 2020). "In addition to somatic mutations, ARID1A loss has also been found in a variety of human tumor types, such as uterine endometrioid carcinomas, uterine clear-cell carcinomas, uterine serous carcinomas, uterine carcinosarcomas, clear cell renal cell carcinoma, prostate cancers and medulloblastomas." (PMID 26569409, 2015). "However, patients with ARID1A-mutant renal clear cell carcinoma had dramatically lower CD8+ T cell infiltrations than those without, indicating the association between ARID1A alterations and immune infiltrates was cancer-dependent." (PMID 31949479, 2020).
endometrial tumors (13 papers, 2012 to 2025). "Specifically, and in line with the observation that ARID1A mutations are found enriched in type‐I endometrial tumors, we focused our analysis on TCGA_UCEC tumors of endometrioid histology." (PMID 35167193, 2022). "Because some authors have postulated that ARID1A has a tumour suppressor role, first we reasoned that altered expression of ARID1A would be associated to endometrial tumour initiation." (PMID 35167193, 2022). "An early functional proteogenomic analysis of endometrial tumor samples with ARID1A mutations using reverse phase protein array demonstrates that ARID1A mutations often co-occur with mutations in the PI3K pathway and are related to PI3K pathway activation." (PMID 34671561, 2021). "In summary, the findings from this study provide molecular insights into how ARID1A inactivation modulates transcription reprogramming to accelerate endometrial tumor progression and dissemination, which are the major causes of cancer mortality." (PMID 32483112, 2020). "The molecular profiles obtained from the TCGA 2013 endometrioid endometrial carcinoma tumor set (n = 193) were similar to the endometrioid SEO molecular profiles (n = 32) for both the endometrial and ovarian counterparts, except for a higher frequency of ARID1A mutations in the endometrial tumors." (PMID 32022266, 2020). "We identify transcriptional networks that are controlled by Arid1a and have an impact on endometrial tumor development." (PMID 32483112, 2020). "This opposite observation was likely due to stromal TGF-β signaling in the mouse endometrial tumors, as the intra-tumoral stromal cells are ARID1A wild-type and responsive to TGF-β stimulation." (PMID 32483112, 2020). "Mutations in PTEN, ARID1A, PIK3CA, PIK3R1, beta-catenin, CTCF, and KRAS, are often found in endometrial tumors with endometrioid histology, with a mutation in at least one of these genes found in 94% of tumors." (PMID 30712080, 2019). "It is important to determine whether the epigenomic landscape is affected by alterations in the ARID1A SWI/SNF complex at different stages of endometrial tumor development or in response to endogenous and exogenous factors such as hormones, obesity, and exposure to infection or carcinogen." (PMID 32483112, 2020). "Using a system biology approach and functional studies, we demonstrate that ARID1A-deficiency lead to loss of TGF-β tumor suppressive function and that inactivation of ARID1A/TGF-β axis promotes migration and invasion of PTEN-deleted endometrial tumor cells." (PMID 32483112, 2020). "Many of these genes appear to be specific to endometrioid endometrial tumors, as opposed to nonendometrioid endometrial tumors, including transcriptional regulators ARID1A, beta-catenin, and CTCF, indicating that there may be a connection between these mutations and estrogen signaling." (PMID 30712080, 2019). "Genes with co-alterations notably enriched in KRASm subsets included STK11 in non-Sq NSCLC, PIK3CA and APC in CRC, and ARID1A, PTEN, and PIK3CA in endometrial tumors." (PMID 36494601, 2022).
urothelial carcinoma (13 papers, 2018 to 2025). A malignant neoplasm derived from the transitional epithelium of the urinary tract (urinary bladder, ureter, urethra, or renal pelvis). "Loss of ARID1A expression in urothelial carcinoma is associated with higher grade and stage, but with no prognostic impact." (PMID 38275587, 2023). "Loss of ARID1A expression was seen in 4 of 14 cases of undifferentiated/rhabdoid urothelial carcinoma in a case series." (PMID 38275587, 2023). "Mutations of SWI/SNF complex genes are seen in 64% of urothelial carcinomas, of which mutations in ARID1A are the most frequent, occurring in 13–38% of cases." (PMID 38275587, 2023). "Recently, Arid1a mutation was reported as a biomarker for sensitivity of platinum-resistant urothelial carcinoma cells to Panobinostat-mediated HDAC targeting." (PMID 32967217, 2020). "Loss of ARID1A expression is associated with higher stage and more aggressive variants of urothelial carcinomas." (PMID 33227989, 2020). "Two recent studies observed a reduction of ARID1A protein expression with increasing grade and stage of urothelial carcinomas associated with worse patient prognosis." (PMID 30138427, 2018). "Erdafitinib, an FGFR inhibitor, is approved for FGFR3-altered urothelial carcinoma, and emerging agents targeting epigenetic alterations such as ARID1A or KMT2D mutations may expand future treatment options." (PMID 41395625, 2025). "We observed increased ARID1A protein levels in all urothelial carcinoma subgroups with strongest expression in early tumor stages compared to NU controls." (PMID 30138427, 2018). "Thus, ARID1A might be used as an additional biomarker for clinical response to both HDAC inhibition and anti-PD-L1 therapy, albeit its function as a biomarker has only been described for patients with advanced urothelial carcinoma yet." (PMID 33227989, 2020).
lymph node metastasis (12 papers, 2012 to 2025). "Inactivating mutations in the gene, as well as complete or partial loss of ARID1A expression, seem to be an important factor promoting lymph node metastasis after invasion and are associated with poor patient prognosis." (PMID 39028418, 2024). "Univariate Cox regression analyses showed that depth of tumor infiltration, local lymph node metastasis, distant metastasis, tumor size and ARID1A expression were significantly associated with overall survival." (PMID 22808142, 2012). "Additionally, ARID1A and EPHA2 mutations were associated with lymph node metastasis of ICC." (PMID 35070505, 2022).
breast tumors (11 papers, 2013 to 2023). "The same lineage switch was found to occur in breast tumors with ARID1A loss, and ARID1A genetic alterations in patients were associated with clinical resistance to selective ER degraders, highlighting the direct clinical relevance of these findings." (PMID 36911295, 2022). "We also evaluated the association between the expression of HuR and ARID1A proteins in vivo using a collection of patient-derived breast tumor xenografts (PDXs) by Western blot analysis." (PMID 31847141, 2019). "Using a hypothesis-generating approach, analyzing 23 breast tumors from Kenyan patients, we discovered an overrepresentation of ARID1A gene mutations." (PMID 37902422, 2023). "Finally, it describes an overrepresentation of ARID1A gene mutations in breast tumors of the Kenyan patients." (PMID 37902422, 2023). "Somatic ARID1A, MLL3 and NF1 mutations were found in at least one component in three, six and four breast tumours, respectively, and the presence of these mutations was unrelated to the HER2 status." (PMID 32058674, 2020). "We found that HuR and ARID1A expression levels are positively correlated in samples of breast tumors and patient-derived xenografts, as well as in other independent studies." (PMID 31847141, 2019). "For example, the exploration of the SWI/SNF complex in breast tumors revealed that ARID1A tends to be mutated in samples where neither SMARCA4, ARID2 nor SMARCA2 are mutated." (PMID 24063517, 2013). "HER2-low breast tumors also had significantly higher mutations rates in CBFB (p < 0.05), PIK3CA (p < 0.05), mitogen-activated protein kinase kinase kinase 1 (MAP3K1; p < 0.05), and AT-rich interaction domain 1A (ARID1A; p < 0.05) as compared with HER2-zero breast tumors." (PMID 35484593, 2022). "Moreover, using GSE32646 data set, among patients receiving paclitaxel‐based NAC, ARID1A mRNA levels in TNBC, but not breast tumour of ER(+) and HER2(+), derived from patients with nCR were significantly (P < .05) decreased compared to those of patients with pCR." (PMID 29392887, 2018).
endometrioid tumor (11 papers, 2017 to 2024). A benign, borderline, or malignant epithelial tumor of the female reproductive system characterized by the presence of glands and/or cysts lined by neoplastic cells that resemble endometrial cells. "All five primary cell line samples showed multiple gene alterations previously associated with endometrioid tumors including ARID1A, PTEN, and SMARCA4." (PMID 39240189, 2024). "For example, WT1 is a marker of serous tumors, and ARID1A is somatically mutated in ∼50% of clear cell and ∼30% of endometrioid tumors." (PMID 29312534, 2017). "Other altered genes labelling the endometrioid cancer were CTNNB1, KRAS, POLE, and ARID1A genes, each of them accepted as genetic biomarker of the endometrioid tumors." (PMID 36010253, 2022).
sarcoma (10 papers, 2020 to 2025). A usually aggressive malignant neoplasm of the soft tissue or bone. "ARID1A is frequently mutated across human cancers, including sarcomas." (PMID 41514647, 2025). "However, data of ARID1A mutations in soft tissue neoplasms are limited and evidence suggest that ARID1A mutations are very rare in sarcomas." (PMID 35125107, 2022). "We also note the unexpected finding that UAS (n = 14), a rare sarcoma subtype, had oncogenic alterations in genes encoding subunits of the SWI/SNF chromatin remodeling complex in 43% of patients, with ARID1A and PBRM1 most frequently affected." (PMID 35705560, 2022). "Inactivation of ARID1A is frequent across carcinomatous types and very rarely drives the tumorigenesis of sarcomas." (PMID 35125107, 2022). "Inclusion of other SWI/SNF immunomarkers, such as ARID1A, in the differential diagnostic workup of poorly differentiated sarcoma not fitting well-known subtypes, such as SMARCB1 and SMARCA4-deficient sarcomas, is recommended." (PMID 35125107, 2022). "Our cohort also included two sarcomas with VIM–KMT2A fusions, each harboring concurrent mutations in CTNNB1, SMARCB1, and ARID1A and characterized histologically by sheets of spindle-to-round blue cells." (PMID 32461620, 2020). "Subsequently, genomic alterations in ARID1A have been described in a broad array of tumor types with the notable exception of sarcomas." (PMID 32393201, 2020). "Interestingly, certain splice isoforms of ARID1A have also been shown to have oncogenic properties in sarcoma." (PMID 33482911, 2021). "In a study of sarcomas, seven proteins related to overall survival (AMPKALPHA, CHK1, S6, ARID1A, RBM15, ACETYLATUBULINLYS40, and MSH6) were discovered using the proteomics data of different sarcoma subtypes." (PMID 35875106, 2022). "ARID1A is the most frequently dysregulated SWI/SNF subunit in human cancer and inactivation of ARID1A is frequent across carcinomatous types while very rarely drives the tumorigenesis of sarcomas." (PMID 35125107, 2022).
uterine cancer (10 papers, 2017 to 2024). Primary or metastatic malignant neoplasm involving the uterine corpus and/or the cervix. "The same pattern was also observed in uterine cancers with ARID1A mutations, which were enriched in a series of 222 cases of uterine cancer with PIK3CA and PTEN mutations." (PMID 34659566, 2021). "SIRT1 expression seems to be associated with improved progression-free survival in uterine cancer (endometrioid and clear-cell) and is correlated to the tumor suppressors β-Catenin and ARID1A." (PMID 32388637, 2020). "Given the frequency of ARID1A mutations in patients with clear cell and endometrioid ovarian and uterine cancer, and the prognostic implications of loss of ARID1A expression, it is natural to explore the impact of EZH2 inhibition in these patient subsets." (PMID 29093822, 2017). "ARID1A loss is particularly common in ovarian clear cell and uterine carcinomas." (PMID 37934611, 2024). "Furthermore, in cancer cell lines from the CCLE database, the frequency of ARID1A damaging mutations ranged from 0%, for example for head and neck cancer cells, up to 62% (23 out of 37 cell lines have ARID1A mutations) for endometrial and uterine cancer cells." (PMID 36980292, 2023).